SDC1 (syndecan 1)
Diseases named in the same sentence as SDC1 in open-access papers (continued):
Sharing a sentence is not in itself a finding about the gene and the disease.
myeloma (continued). "Interestingly, recent insights into the effects of heparanase-induced shedding of syndecan-1, an HSPG implicated in the pathobiology of multiple myeloma, revealed a unifying mechanism whereby heparanase expression promotes different aspects of disease progression." (PMID 30413079, 2018). "Furthermore, the ability of roneparstat to inhibit multiple myeloma growth and angiogenesis has been correlated with disruption of the heparanase/syndecan-1 axis and downregulation of HGF, VEGF and MMP-9 gene expression controlled by endogenous heparanase in myeloma cells." (PMID 27374103, 2016). "A phase I/II radioimmunotherapy study using B-B4 conjugated to iodine-131 was conducted in refractory multiple myeloma patients and significantly improved clinical outcome than the control group, suggesting that targeted radioimmunotherapy is feasible using an anti-SDC1 monoclonal antibody." (PMID 26293675, 2015). "Moreover, shed syndecan-1 secreted by myeloma cells may also bind OPG and block its inhibitory activity to RANKL triggering further osteoclast differentiation and activation." (PMID 23862137, 2013). "Syndecan-1 driven upregulation of serglycin (the only constitutively intracellular proteoglycan) in mesothelioma cells can be an important new finding for cancer cell biology, as there are only a few reports linking serglycin to tumors, mostly to multiple myeloma and nasopharyngeal carcinoma cells." (PMID 23144729, 2012). "A prognostic value has been assigned to changes in syndecan-1 expression in several cancer types, including breast, colorectal, gastric, pancreatic, prostate, lung, endometrial, and ovarian cancers, as well as squamous cell carcinoma of the head and neck and multiple myeloma." (PMID 22214534, 2011). "Shedding of SDC-1 exposes a latent domain that promotes the interaction of VEGFR2 with α4β1 integrin, leading to the activation of the VEGF-2 receptor in both myeloma and endothelial cells." (PMID 41301515, 2025). "MM cells also degrade osteoprotegerin (OPG), a soluble decoy receptor for RANKL that antagonizes osteoclastogenesis, after internalizing it via binding to heparan sulfate proteoglycans (HSPGs), such as syndecan-1 (CD138), on the myeloma cell surface." (PMID 40862742, 2025). "Studies in myeloma models revealed dual roles for HPSE in HGF activity: high serum levels of HPSE, shed SDC-1, and HGF correlate with poor prognosis, reflecting functional cooperation." (PMID 41301515, 2025). "Separate findings indicated that primary bone marrow stromal cells from patients with myeloma and the bone marrow stromal cell line HS5 express high levels of syndecan-1 and heparan sulfate." (PMID 38912739, 2024). "For example, TXNDC11 and CCR10 protein levels appear stable across drug treatments in comparison to canonical myeloma markers BCMA and CD138/SDC1." (PMID 35840578, 2022). "Syndecan-1 (SDC1), also known as CD138, can induce an immature and stem cell-like transcriptional program in myeloma cells." (PMID 36388159, 2022). "In myeloma cells, HGF binds to cell surface-bound SDC-1 with the resultant SDC-1/HGF complex stimulating cell migration via the c-Met receptor upon SDC-1 cleavage." (PMID 35118073, 2021). "Syndecan-1 is another cell-surface HSPG that has been revealed to be a potential immunotherapeutic target for cancer therapy, more specifically for multiple myeloma." (PMID 34858858, 2021). "Perhaps the greatest impact of Sdc1-coupled IGF-1R on tumorigenesis is its role in tumor survival, revealed in myeloma cells that express high levels of Sdc1 (CD138) and constitutively active Sdc1-coupled IGF-1R." (PMID 34778093, 2021). "For example, syndecan-1, also known as CD138, has been described to be present in multiple myeloma, breast, colorectal, and pancreatic carcinomas, among others." (PMID 33669066, 2021). "CD19, SDC1 (CD138), CD38, SLAMF7, and TNFRSF17 (BCMA) were selected for targeting multiple myeloma (MM)." (PMID 34975912, 2021).
myeloma (continued). "HGF expression by myeloma cells is significantly elevated by HPSE, which facilitates the HGF binding by myeloma cell surface syndecan-1, a member of HSPGs, leading to HGF-enhanced myeloma tumor cell growth." (PMID 32626713, 2020). "For example, in multiple myeloma, heparanase trimming of the Sdc1 HS chains allows MMP−9-mediated shedding of Sdc1." (PMID 33243988, 2020). "Recent studies indicate that the interplay between the cell surface proteoglycan Syndecan-1 (Sdc-1) and HPSE have important functional connections in the progression of colorectal cancer and myeloma." (PMID 32477959, 2020). "They postulated that Syndecan-1 expressing myeloma cells bind, internalize and degrade OPG in vitro and in vivo as concluded from lowered OPG level in serum of patients with multiple myeloma." (PMID 33239699, 2020). "For example, syndecan-1 that is expressed on AML cells, is a therapeutic target under investigation in multiple myeloma, while the inhibition of ILK has been tested in chronic lymphocytic leukaemia, prostate, and breast cancer cell lines." (PMID 30658474, 2019). "For exmaple, SDC1 binds to VEGF, and SDC1 shedding increases the VEGF concentration in the matrix and promotes angiogenesis in myeloma." (PMID 30197623, 2018). "A likely target of the enzyme is the heparan sulfate (HS) proteoglycan syndecan-1 (Sdc1, CD138), which is highly expressed on myeloma cells and contributes to poor prognosis in this disease." (PMID 26926788, 2016). "Testing this, we find that HMEC-1 cells express levels of HPSE equivalent to the HPSEhigh myeloma cells and that conditioned medium from the HMEC-1 cells contains shed Sdc1, which is abolished upon treatment with the HPSE inhibitor Roneparstat." (PMID 26926788, 2016). "We previously demonstrated that MM cell-derived HPSE not only induced an aggressive phenotype in myeloma cells, but also promoted angiogenesis via the secretion of soluble factors, such as HGF, VEGF and soluble syndecan-1, from myeloma cells." (PMID 26849235, 2016). "Serum SDC1 and bFGF/FGF2 levels were elevated in multiple myeloma patients before treatment compared to the control group." (PMID 26293675, 2015). "Bone marrow levels of soluble SDC1 and HGF were elevated in multiple myeloma patients compared to control subjects." (PMID 26293675, 2015). "Experimental infection of terminally differentiated tumor derived B cells (multiple myeloma, MM) with EBV virus in vitro results in down-regulation of syndecan-1/CD138 expression." (PMID 26527314, 2015). "Another interesting candidate for further investigation is CSGALNACT1 which encodes a protein involved in the initial synthesis of chondroitin sulphate, a component of Syndecan-1 (CD138), also known as a central player in multiple myeloma pathogenesis." (PMID 24376673, 2013). "In addition, screening of multiple myeloma surface antigens has identified other promising targets, including CD28 (Tp44), CD48 (BLAST), CD74 (CLIP), CD138 (SDC1), CD229 (SLAMF3), CD319 (SLAMF7), CCR10 (GPR2), TAC1 (NPK), TXNDC11, SLC1A5 (AAAT)." (PMID 41369346, 2025). "A targeted proteomic approach using a mass cytometry panel of myeloma response markers after a 24-h exposure to ProRS inhibitors supports and extends the observed changes in the protein abundance of MYC, MCL-1 and SDC1." (PMID 36631435, 2023). "For instance, when myeloma cells were exposed to chemo-exosomes, the heparanase cargo was transferred, resulting in increased heparan sulfate degrading activity, ERK signaling activation, and increased shedding of syndecan-1 proteoglycan." (PMID 37612627, 2023). "Furthermore, we found downregulation of SDC1 and TCF3 and upregulation of DDIT3 in the myeloma cluster, consistent with the observations in MM cell lines." (PMID 36631435, 2023).
myeloma (continued). "Several epitopes, such as syndecan-1 (CD138), X-box–binding protein 1 (XBP1)-unspliced, XBP1-spliced, CS1, have been identified as potential targets in multiple myeloma (MM) and smoldering multiple myeloma (SMM), and their applications against MM and SMM were also very effective." (PMID 35814435, 2022). "Validating our strategy, we identified nearly all known canonical diagnostic markers and immunotherapeutic targets in myeloma, including BCMA, CD138/SDC1, CD38, CD56, SLAMF7/CS-1, CD46, Integrin-b7 (ITGB7), CD74/HLA-DR, TACI, CD48/ SLAMF2, and LY9/CD229." (PMID 36311892, 2022). "In myeloma cells, elevated levels of VEGF and shed SDC-1 activate endothelial cells." (PMID 33562126, 2021). "NK and T-cells express Sdc1, VEGFR2, CXCR4, AC7 and HPSE and their LFA-1-mediated migration in in vitro invasion assays is dramatically increased by SSTNVEGFR2 while at the same time the peptide inhibits the VLA-4-mediated invasion of myeloma cells." (PMID 34778093, 2021). "A pre-assembled complex consisting of Sdc1, inactive αvβ3 or αvβ5 integrin and inactive IGF-1R is found in fibroblasts, breast cancer and other carcinomas, multiple myeloma and activated vascular endothelial cells undergoing pathological angiogenesis and is likely found in many cancers." (PMID 34778093, 2021). "Studies in multiple myeloma and breast and colon cancer detected specific proteases, including MMP-7, which is synthetized by the tumor cells, and is able to proteolytically remove the ectodomain of SDC1." (PMID 33114033, 2020). "For example, as multiple myeloma cells are marked by CD38+/CD138+ antigen expression, they could be distinguished by the codetection of high CD138 (SDC1) and CD38 gene expression in scRNA-seq data." (PMID 32929226, 2020). "High levels of soluble SDC1 and lower expression of cellular SDC1 at the time of diagnosis are negative prognostic factors for multiple myeloma." (PMID 26293675, 2015). "Heparanase induces SDC1 shedding, and soluble SDC1 is an independent negative prognostic factor in multiple myeloma." (PMID 26293675, 2015). "In addition, HGF existed in a complex form with soluble SDC1 in pleural effusions, suggesting an important role of soluble SDC1 as a carrier for HGF in the pathology of myeloma." (PMID 26293675, 2015). "In some ways, the co-upregulation of FGF2 and SDC1 seen in tissue biopsies and PBL (albeit at the mRNA level) of PO NS-cHL patients in our study may be related to certain features of multiple myeloma." (PMID 23988031, 2013). "A novel mechanistic pathway driven by heparanase expression in myeloma cells can induce elevated levels of VEGF and shedding of syndecan-1 from matrix-anchored complexes that together activate integrin and VEGF receptors on adjacent endothelial cells, thereby stimulating tumor angiogenesis." (PMID 22773903, 2012). "SDC1 and its encoded protein syndecan-1 (CD138) are overexpressed in mesothelioma and myeloma, but downregulation rather than overexpression has been linked to drug resistance." (PMID 22905093, 2012). "Detection of syndecan-1 has become a useful tool in the diagnosis of some hematological malignancies, since syndecan-1 is expressed in plasmacytoma/plasma cell myeloma, but absent in most types of non-Hodgkin lymphomas." (PMID 22777011, 2012). "The B-B4 mAb has been shown to have high specificity for syndecan-1, but it is not cytotoxic for myeloma cells." (PMID 22214534, 2011). "Syndecan-1 has not been previously reported to be localized in the nucleus of myeloma cells or in myeloma patient tumor cell samples." (PMID 19305494, 2009). "In addition, in vitro studies showed that shed SDC1 may bind VEGF stimulating endothelial invasion and tumor angiogenesis in myeloma cells." (PMID 36353562, 2022).
myeloma (continued). "Notably, across these lines we detected almost all of the major immunotherapy targets in myeloma, as well as canonical flow cytometry markers for plasma cells: BCMA, CD138/SDC1, CD38, CD56, SLAMF7/CS-1, CD46, Integrin-b7 (ITGB7), CD74/HLA-DR, TACI, CD48/SLAMF2, and LY9/CD229." (PMID 35840578, 2022). "This drug, approved for the clinical treatment of patients with multiple myeloma and bone metastases, also inhibits BC growth, migration and invasion by targeting various ECM proteins, including integrins ανβ3, ανβ5, and α5β1, and Sdc-1, and by suppressing the expression of MMP-2 and MMP-9." (PMID 32604738, 2020). "But whether it is the cell surface or the shed form of Sdc1 that mediates the potent effect of HPSE on myeloma progression is not clear." (PMID 26926788, 2016). "Thus, despite the clinical relevance of syndecan-1 in the prognosis of diseases such as multiple myeloma, and sepsis, syndecan-1 does not appear to be important in PD-induced pathology." (PMID 26832929, 2016). "Given the emerging role of Sdc1 as an organizer of matrix- and growth factor-dependent signaling, we speculated that the tumor-promoting activity of HPSE may trace to its activation of such a mechanism during myeloma cell adhesion and invasion." (PMID 26926788, 2016). "Since the truncated form of SDC1, which is found in multiple myeloma, does not have an ectodomain, biological effects of SDC1 on malignant behavior of tumor cells may be dependent on the status of SDC1 size." (PMID 24373193, 2013). "While TNFRSF17 (BCMA) was highly specific for myeloma samples, other immunotherapy targets such as CD38, CD138 (SDC1) and SLAMF7 were not or only moderately higher expressed in MM versus healthy plasma cells." (PMID 38942927, 2024). "Several key questions about this activation mechanism remain unanswered, including how clustering of Sdc1 activates IGF1-R independent of IGF1 ligand, how SSTNIGF1R blocks IGF1 stimulation of IGF-1R in myeloma and whether SSTNIGF1R blocks IGF1-induced IGF-1R activation in tumors other than myeloma." (PMID 34778093, 2021).
breast carcinoma (184 papers, 2005 to 2026). "The expression of SDC1 was significantly associated with breast cancer subtype and this gene was found to be associated with overall survival (OS) in most analyzed cancers." (PMID 41364407, 2025). "For luminal breast cancer patients, tumor cell SDC1 expression was positively associated with OS and EFS, but this was not the case for HER2 + and triple-negative patients." (PMID 41364407, 2025). "In breast cancer, increased expression of SDC1 on the cell surface was associated with reduced overall survival in ER‐ cells, while higher levels of stromal SDC1 indicate poor survival prognosis for patients with ER+ cancer." (PMID 40542654, 2025). "Subsequent analyses will focus on elucidating the underlying mechanisms through which SDC1 contributes to adverse outcomes in breast cancer patients." (PMID 41209699, 2025). "SDC1 expression levels have been found to be greater in breast cancer and to be associated with a worse prognosis for breast cancer patients." (PMID 38639039, 2024). "Transforming growth factor beta (TGF-β) signaling was implicated in the regulation of CHPF and SDC1 in breast cancer cells." (PMID 38770553, 2024). "Results indicated that the expression of CHPF and SDC1 was tightly associated within primary breast cancer tissue, and high expression of both genes exacerbated patient prognosis." (PMID 38770553, 2024). "In breast cancer, high SDC1 expression has been shown to be associated with aggressive tumors and poor prognosis." (PMID 37056938, 2023). "This leads authors to suggest that either single or dual inhibition of heparanase and SDC1 can suppress the risk of breast cancer (progression) in individuals (patients) with high mammographic density." (PMID 36980680, 2023). "Elevated levels of syndecan expression in cancer can correlate with poor outcomes: Syndecan-1 in breast cancer and Syndecan-2 in colorectal cancer are highly associated with metastasis." (PMID 37298452, 2023). "For the remaining two BM genes (PXDNL and SDC1), our data indicated that high expression was associated with unfavorable prognoses in breast cancer." (PMID 37056938, 2023). "For instance, in gastric and colorectal cancer a reduced expression of SDC1 is associated with advanced stages, whereas in pancreatic and breast cancer its overexpression was found to promote cell growth and proliferation." (PMID 35328227, 2022). "Syndecan-1 is a membrane-bound proteoglycan associated with an aggressive phenotype and poor prognosis in breast cancer." (PMID 34113616, 2021). "SDC1 has been implicated in promoting breast cancer progression and is highly expressed in basal-like breast cancers." (PMID 34113616, 2021). "In line with previous studies of our laboratory, Sdc-1 depletion affected the breast cancer stem cell phenotype, associated with therapeutic resistance." (PMID 34070901, 2021). "Blood vessels arising from tumor angiogenesis are a potential source, but in some cases, e.g., advanced breast cancer, some syndecan-1 is clearly associated with the collagenous extracellular matrix." (PMID 33921767, 2021). "Here, we studied the effect of Sdc-1 siRNA depletion and HA treatment on hallmark processes of cancer in breast cancer cell lines of different levels of aggressiveness." (PMID 34070901, 2021). "Clinically, the same study confirmed this finding in primary human breast cancer specimen, where stromal Sdc-1 expression was significantly associated with tumor vascularity (i.e., both vessel density and total vessel area)." (PMID 34066023, 2021). "A meta-analysis synthesized the data of 1,305 breast cancer patients from nine studies and revealed that high SDC1 expression has been associated with poor prognosis in breast cancer." (PMID 32596149, 2020). "SDC1, another EMT marker identified in this study, can be used to assess the tumor prognosis, including breast cancer, wherein increased expression levels of SDC1 are associated with the worst prognosis." (PMID 33092068, 2020).